CUL3 (cullin 3)
Diseases named in the same sentence as CUL3 in open-access papers (continued):
Sharing a sentence is not in itself a finding about the gene and the disease.
CUL3 also shares sentences with these, for which no sentence is quoted: Hyperkalemia (5 papers); acute kidney injury (2); colon cancer (2); head and neck squamous cell carcinoma (2); metabolic acidosis (2); metabolic disease (2); Acidosis (1); acute coronary syndrome (1); acute myeloid leukemia (1); adrenocortical tumors (1); angina pectoris (1); cardiac disease (1); cardiovascular disease (1); CEDNIK syndrome (1); chronic kidney disease (1); congenital heart disease (1); electrolyte imbalances (1); esophageal cancer (1); essential hypertension (1); fibrosarcoma (1); Hematuria (1); hereditary disease (1); intracerebral hemorrhage (1); intrauterine growth retardation (1); kidney cancer (1); leiomyoma (1); lymphoma (1); microcephaly (1); multiple myeloma (1); myeloid malignancies (1).
A further 20 diseases each share a sentence with CUL3 in 1 paper.